TRAPPC3L (trafficking protein particle complex subunit 3L)
Description:
May play a role in vesicular transport from endoplasmic reticulum to Golgi.
Synonyms: BET3L; bA259P20.2; FLJ11180
Tractability: PROTAC: ubiquitination databases record sites on it.
Gene: Protein-coding gene on chromosome 6 (116,494,989 to 116,545,684, reverse strand). Ensembl gene ENSG00000173626.
Subcellular location: Golgi apparatus, cis-Golgi network; Endoplasmic reticulum
Subcellular location (Human Protein Atlas): Golgi apparatus; Vesicles
Gene Ontology:
Molecular function: protein binding; guanyl-nucleotide exchange factor activity
Biological process: endoplasmic reticulum to Golgi vesicle-mediated transport; intra-Golgi vesicle-mediated transport; Golgi vesicle transport
Cellular component: TRAPP complex; cis-Golgi network membrane; cytosol; endoplasmic reticulum; Golgi apparatus
Genetic constraint (gnomAD): Loss-of-function variants: 19 observed, 18.79 expected, observed/expected ratio (o/e) 1.01, 90% interval 0.7 to 1.48. The upper end of that interval is the gene's LOEUF score, 1.48, which puts it in group 6 of 6, group 1 being the genes least tolerant of losing a copy. Missense variants: 195 observed, 203.22 expected, observed/expected ratio (o/e) 0.96, 90% interval 0.85 to 1.08. Synonymous variants: 74 observed, 75.33 expected, observed/expected ratio (o/e) 0.98, 90% interval 0.81 to 1.19.
Homologues: Orthologues: macaque TRAPPC3L (98% identical), dog TRAPPC3L (95% identical), rabbit TRAPPC3L (93% identical), mouse Trappc3l (93% identical), pig TRAPPC3L (92% identical), rat Trappc3l (92% identical), chimpanzee TRAPPC3L (90% identical), guinea pig TRAPPC3L (87% identical), tropical clawed frog trappc3l (69% identical), Drosophila melanogaster Bet3 (46% identical), Caenorhabditis elegans trpp-3 (39% identical). Paralogues in human: TRAPPC3 (62% identical).